TIMP1 (TIMP metallopeptidase inhibitor 1)
Diseases named in the same sentence as TIMP1 in open-access papers (continued):
Sharing a sentence is not in itself a finding about the gene and the disease.
ovarian carcinoma (continued). "Adipokines, such as IL-6, IL-8, monocyte chemoattractant protein-1 (MCP-1), tissue inhibitor of metalloproteinase-1 (TIMP-1), and adiponectin in the ovarian cancer microenvironment can promote cancer cell growth by activating fatty acid production in adipocytes." (PMID 35216285, 2022). "A study on the effect of cisplatin on the invasion of ovarian cancer cells showed that the use of cisplatin could reduce the expression of TIMP1 by 5.0 times (p < 0.05)." (PMID 36238159, 2022). "There are very limited data on blood levels of TIMP-1 and ascites in patients with ovarian cancer." (PMID 34572929, 2021). "Further research in this area may provide a better understanding of the function of TIMP-1 in the development and metastasis of ovarian cancer, as well as resistance to chemotherapy." (PMID 34572929, 2021). "This may suggest that TIMP-1 in ovarian cancer may well be in the tumor secretome in contrast to being retained in the tissues." (PMID 35047406, 2021). "In addition, TIMP-1 overexpressed and secreted by platinum resistant ovarian cancer altered migration of cancer cells and facilitated the growth of endothelial cells." (PMID 35047406, 2021). "Finally, we demonstrated in vitro and in vivo that TIMP1, one of the genes characterizing the CTCs population, promotes proliferation of ovarian cancer cells, suggesting its potential as a therapeutic target." (PMID 32423054, 2020). "Therefore, in our study, we used SKOV3 cell line as a cellular model and down-regulated TIMP1 expression with the goal of shedding new light on the role of this metalloproteinase in ovarian cancer." (PMID 32423054, 2020). "The increased serum level of TIMP-1 is also detected in ovarian cancer." (PMID 28538838, 2017). "Transcription of TIMP1 (TIMP metallopeptidase inhibitor 1) has previously been shown to be up-regulated by ITGB3 in the ovarian cancer cell line MDAH 2774 and thus may be a candidate target." (PMID 25874946, 2015). "However, these two prior studies investigated TIMP-1 levels in serum and plasma in a smaller population including only 59 and 40 ovarian cancer patients, respectively." (PMID 20459644, 2010). "Only very limited published data exist on the prognostic value of TIMP1 in ovarian cancer." (PMID 20459644, 2010). "Vascular endothelial growth factor (VEGF) and tissue inhibitor of metalloproteinase-1 (TIMP-1) are involved in these processes and might therefore serve as potential biomarkers in ovarian cancer patients." (PMID 20388222, 2010). "We could demonstrate for the first-time that changes of VEGF-165 and TIMP-1 during first-line therapy of ovarian cancer are substantial and closely correlated." (PMID 20388222, 2010). "We further examined whether Timp1 and Lcn2 were enriched in fluid extracted from late stage ovarian tumors and in peritoneal ascites given the proximity of these fluids to ovarian cancer cells and the secreted nature of the proteins." (PMID 19936259, 2009). "In SKOV3 ovarian cancer cells, phlorotannins suppressed migration and invasion by approximately 40 to 60%, accompanied by reduced MMP expression linked to IL-17RA–Act1 signaling attenuation and by increased TIMP1 expression in association with transient ERK1/2 activation." (PMID 41590709, 2025). "However, the mechanisms of how TIMP1 contributes to ovarian cancer are not yet fully understood." (PMID 38172678, 2024). "However, no prior studies have investigated the association between TIMP-1 immunoreactivity and patient prognosis in epithelial ovarian cancer patients." (PMID 20459644, 2010). "In the present study, TIMP-1 expression was detected by means of immunohistochemical staining in TMA made from paraffin blocks of primary ovarian cancer specimens which may be one explanation of the differences compared to studies evaluating levels of TIMP-1 in blood samples." (PMID 20459644, 2010).
ovarian carcinoma (continued). "The combination of the pan-PI3K inhibitor LY294002 with cisplatin effectively inhibits the proliferation and migration of ovarian cancer cells by downregulating the expression of Matrix Metalloproteinase-2 (MMP-2), TIMP1, and TIMP2." (PMID 40656893, 2025). "In this study, we also show that cisplatin (CIS) and paclitaxel (PTX) enhanced the expression of TIMP-1 and TIMP-2 at the protein level in all four ovarian cancer cell lines studied." (PMID 35047406, 2021). "In a study in 37 patients aged 29 to 78 years with epithelial ovarian cancer at the FIGO I (1 case), FIGO II (1 case), FIGO III (29 cases) and FIGO IV (6 cases) stages, concentrations of TIMP-1 in blood serum were determined." (PMID 34572929, 2021). "The databases were searched for the following keywords: ascites, ovarian cancer, cytokines, adipokines, adiponectin, interleukin 6 or IL-6, interleukin 8 or IL-8, MCP-1, TIMP-1, concentration, level." (PMID 34572929, 2021). "From them, CK19, MUC1, CD24, CD44, TIMP1, and CXCR4 appeared, characterizing the ovarian cancer circulating population." (PMID 32423054, 2020). "Both MMP-2 and MMP-9 were enhanced in one of the ovarian cancer cell lines (SKOV3) in response to gonadotropins, while TIMP-1 and TIMP-2 were down regulated, suggesting an inverse relationship between MMPs and their endogenous inhibitors." (PMID 29393911, 2018). "We therefore, used a translational approach to analyze the epithelial and stromal expressions of MMP-2, MMP-7, MMP-9, MT1-MMP, TIMP-1 and TIMP-2 in advanced epithelial ovarian cancers and to assess their prognostic value." (PMID 22200690, 2012). "We set out to analyze the epithelial and stromal expression of MMP-2, MMP-7, MMP-9, MT1-MMP, TIMP-1 and TIMP-2 in advanced epithelial ovarian cancers and to assess their prognostic value." (PMID 22200690, 2012). "The application of serum TIMP-1 and VEGF to monitor primary therapy and predict clinical outcome of patients with ovarian cancer is unclear." (PMID 20388222, 2010). "TIMP-1 and VEGF serum levels changed significantly during first-line therapy of ovarian cancer patients and predicted prognosis." (PMID 20388222, 2010). "In addition to MMPs, several TIMPs, including TIMP1 and TIMP3, have been found upregulated in ovarian cancer." (PMID 40558552, 2025). "Others: GPC3 knockdown in ovarian cancer cells can lead to an increase in the expression of matrix metalloproteinase 2 (MMP-2) and MMP-9, along with a decrease in the level of tissue inhibitors of metalloproteinase 1 (TIMP-1)." (PMID 40422229, 2025). "No quantitative data were found in the literature for the TIMP-1 levels in ascites in ovarian cancer." (PMID 34572929, 2021). "Once the presence of EpCAM positive CTCs in the blood of patients was confirmed using two methodologies, an expression profile analysis, including a panel of genes related to cell plasticity and ovarian cancer aggressiveness (MUC1, CK19, CXCR4, TIMP1, ALDH1, CD24, CD44, GDF1), was carried out." (PMID 32423054, 2020). "TIMP-1 immunoreactivity in tumour tissue from patients with primary epithelial ovarian cancer did not correlate with patient survival or response to combination platinum/cyclophosphamide therapy." (PMID 20459644, 2010). "We demonstrate here that TIMP-1 protein is present in the tumour tissue in a subgroup of ovarian cancer patients but its presence is neither correlated with overall survival nor CA-125 determined response or with objective response to combination chemotherapy with carboplatin and cyclophosphamide." (PMID 20459644, 2010). "Thus, ovarian cancer cells can stimulate monocytic cells in vitro to make proMMP-9 without affecting the expression of its inhibitor TIMP-1." (PMID 9743290, 1998).
ovarian carcinoma (continued). "Interestingly, since the axis CXCR4/SDF1 has been described as an important element for the apoptosis inhibition mediated by TIMP1, we hypothesize that both TIMP1 and CXCR4 expression in CTCs from ovarian cancer patients could be playing an important role for avoiding apoptosis phenomena." (PMID 32423054, 2020). "In our study, miR-320a expression in the intraperitoneal fluid of ovarian cancer patients had a negative correlation with RANTES, TIMP-1, and IL-6." (PMID 37298699, 2023).
renal fibrosis (42 papers, 2010 to 2026). A final common manifestation of a wide variety of chronic kidney diseases characterized by glomerulosclerosis and tubulointerstitial fibrosis. "Similarly to IS, PCS increases the production of inflammatory cytokines (TGF-β1, TIMP-1, pro-α-1(I)-collagen), causing renal fibrosis." (PMID 36983311, 2023). "A recent study showed that long-term low-grade inflammation, with sustained increased PTX3 levels, may underlie renal fibrosis in ESRD due to a MMP-9/TIMP-1 imbalance." (PMID 31316299, 2019). "However, the underlying mechanism by which TIMP1 involves in renal fibrosis remains further investigation." (PMID 27649757, 2016). "Another study defining the role of cytokine cardiotrophin 1, in cardiac, vascular, and renal function found increased renal fibrosis with cardiotrophin 1 infusion which was associated with a decreased MMP-13/TIMP-1 ratio suggesting a protective role in this model." (PMID 24159376, 2013). "Meanwhile, miR-4483 was decreased in fibrotic kidneys and HG or TGF-β1-treated HK-2 cells, whereas TIMP1 was inhibited by miR-4483 at both mRNA and protein levels, which may be the underlying mechanism that miR-4483 is involved in renal fibrosis, which requires further research." (PMID 38316653, 2024). "Nevertheless, the strong correlation found between the PTX3 levels and circulating TIMP-1 in our cohort of dialysis patients, as well as the regression data from the predictive analysis, supports a possible association between this modulator and renal fibrosis in ESRD patients." (PMID 31316299, 2019). "Kl and Clu contribute antiaging and antifibrotic effects in kidneys and Timp1 and Timp2 participate in remodeling the extracellular matrix, impacting renal fibrosis." (PMID 41567268, 2026). "Among them, the functions of Fn, Timp1, C3, Apoe, Trf, and Fbn1 were already previously thoroughly studied in renal fibrosis." (PMID 40564035, 2025). "In conclusion, it indicates that miR-1470 can bind directly to MMP13, while miR-4483 binds to TIMP1 and thus is involved in renal fibrosis." (PMID 38316653, 2024). "COL4A2, CXCL1, TIMP1, VCAM1, and VEGFA are promising diagnostic biomarkers of tissue and serum for renal fibrosis." (PMID 37266443, 2023). "In diabetic rats, the levels of the fibrosis-related factors TGF-1, PDGF, and TIMP-1 can be decreased by renin-angiotensin-aldosterone system inhibitors, which can also be used to treat renal fibrosis." (PMID 37266443, 2023). "In HK-2 cells, rhein inhibited high-glucose-induced EMT by inhibiting ILK expression and regulating the MMP-9/TIMP-1 ratio to relieve renal fibrosis." (PMID 36235108, 2022). "In this study, we also identified that the regulation of fibrosis via targeting MMP13 and TIMP1 may be the mechanisms by which miR-1470 and miR-4483 are involved in the process of renal fibrosis." (PMID 38316653, 2024). "In short, COL4A2, CXCL1, TIMP1, VCAM1, and VEGFA are promising diagnostic biomarkers of tissue and serum for renal fibrosis, which is helpful for the early diagnosis and treatment of patients with renal fibrosis." (PMID 37266443, 2023). "The ratio of MMP-9/TIMP-1 is considered as a potential indicator for evaluating renal fibrosis." (PMID 36235108, 2022). "Hnf4α, Pck1 and Timp-1 may play a pivotal role in the early activation of fibroblasts, providing novel therapeutic strategies for early prediction and treatment of renal fibrosis." (PMID 33777519, 2021). "Monitoring of urinary and serum MMP-2, -9 and MMP-2, -9/TIMP-1, -2 ratios may become useful in determining the progression of renal fibrosis and better stratification of patients with ON." (PMID 32670438, 2020). "Similarly, renal fibrosis was increased in all kl/kl mice and mRNA expression of markers of fibrogenesis such as Timp1, Col1a2 and Fn1 were elevated in kl/kl kidneys independently of the presence of FGFR4." (PMID 31575945, 2019).
renal fibrosis (continued). "We also found that T1Col, αSma, Timp-1 and Timp-2 were significantly increased in kidney of the mice receiving Ang II infusion compared to vehicle treated mice, consistent with the presence of renal fibrosis." (PMID 30120363, 2018). "It is suggested by the results that abnormal expressions of MMP-2 and TIMP-1 might play roles in the development of renal fibrosis in chronic AMR." (PMID 23057632, 2012). "COL4A2, CXCL1, TIMP1, and VCAM1 have all been shown to be elevated in renal fibrosis, which is consistent with the findings of our experimental study." (PMID 37266443, 2023). "After 6 months, the treated group showed increased levels of MMP-2 and MMP-9, reduced levels of TIMP-1, TIMP-2, and TGF-β/Smad signalling, improved renal fibrosis and enhanced renal function." (PMID 37196129, 2023). "Five genes (COL4A2, CXCL1, TIMP1, VCAM1, and VEGFA) were subsequently identified as biomarkers for renal fibrosis through machine learning, and their expression levels were confirmed by validation cohort data sets and in vitro RT-qPCR experiment." (PMID 37266443, 2023). "As observed in animal models of renal fibrosis, several inflammatory mediators, including ICAM-1, are substrate of TIMPs and induce tissue inflammation and damage upon TIMP-1 stimulation." (PMID 36430485, 2022). "Previous studies have shown that in the process of renal fibrosis, the expression of MMP-9 and TIMP-1 were both increased, which resulted in an imbalanced/decreased MMP-9/TIMP-1 ratio and led to reduced capacity of MMP-9 to degrade ECM." (PMID 34082748, 2021). "The disequilibrium between the increased expression of TIMP1 and the inhibited expression of MMP7 is likely to lead to an imbalance in the production and degradation of the extracellular matrix, which in turn promotes renal fibrosis." (PMID 37104396, 2023). "In addition, it downregulated the expression of major fibrotic signaling factors, such as α-SMA, collagen I, MMP-2, and TIMP-1, and significantly regulated the TGF-β1/Smad pathway, which is known as a major regulator of renal fibrosis." (PMID 35572722, 2022). "Studies had found that TMP could inhibit the high expression of TIMP-1 and the imbalance of MMP-9/TIMP-1 ratio in UUO model rats, and thereby slow the progression of renal fibrosis." (PMID 35145414, 2022). "Furthermore, renal gene expression representing markers of renal fibrosis and inflammation, such as COL1A1, COL1A3, TIMP1 and TGF-β, are significantly increased in 5/6 Nx rats compared to 5/6 Nx mice." (PMID 32099009, 2020). "Additionally, in a renal fibrosis model, ICAM-1 was upregulated as one of the substrates of TIMP-1." (PMID 36902508, 2023). "Immunohistochemical and RT-PCR results showed increase of MMP9 and decrease of its tissue inhibitor TIMP-1, thereby leading to an enhanced ratio of MMP/TIMP and hence degradation of extracellular matrix (ECM), which may be important for preventing renal fibrosis." (PMID 30466397, 2018).
asthma (41 papers, 2010 to 2025). "In conclusion, our bioinformatics analysis identified NOS2, TCN1, CHI3L1 and TIMP1 as potential diagnostic biomarkers for asthma and UC." (PMID 40443529, 2025). "Aligned with this, a dysregulated balance of the MMP9/TIMP1 ratio in sputum has been shown to associate with airway remodeling and asthma exacerbation." (PMID 35387021, 2021). "Increased TIMP-1 levels associated with airflow obstruction were found in sputum from subjects with asthma and chronic bronchitis." (PMID 24915862, 2014). "In addition, we identified NOS2, TCN1, CHI3L1, and TIMP1 as possible diagnostic markers for UC and asthma." (PMID 40443529, 2025). "Such architecture of the network indicates that the revealed key nodes are related to four different compartments of the asthma-associated regulome and some of them (Timp1, F5, Ccl12, Ccl6, Ccl9, Adra2a, and Ear1) can be involved in the regulation of similar processes." (PMID 35625754, 2022). "Taken together, MMPs (mainly MMP-9) and TIMP-1 may contribute to progressive loss of lung function and increased cellular matrix fibrosis of the airway wall in chronic asthmatics who demonstrated a poor response to anti-asthma treatments." (PMID 31547356, 2019). "The results showed that only four genes (NOS2, TCN1, CHI3L1, TIMP1) showed statistically significant differences in expression in the data sets validated by asthma and UC compared with the control group." (PMID 40443529, 2025). "GSEA analysis showed that NOS2, TCN1, CHI3L1 and TIMP1 were jointly involved in cytokine receptor interaction in asthma and ulcerative colitis chemokine signaling pathway." (PMID 40443529, 2025). "In conclusion, NOS2, TCN1, CHI3L1 and TIMP1, as key immune and inflammatory regulatory targets, play an important role in the comorbidity of asthma and ulcerative colitis." (PMID 40443529, 2025). "This study highlights NOS2, TCN1, CHI3L1, and TIMP1 as potential biomarkers and therapeutic targets for asthma and UC, providing insights into shared mechanisms and new strategies for diagnosis and treatment." (PMID 40443529, 2025). "The imbalance between MMP-9 and TIMP-1 is recognized as an important theory to explain the development of airway remodeling in asthma." (PMID 36945930, 2023). "TIMP-1 antagonizes MMP-9 activity, and the finding of lower MMP-9/TIMP-1 ratios in the sputum of smokers with asthma suggests that excessive TIMP-1 production occurs as a defense against MMP-9 production in these patients." (PMID 36945930, 2023). "Venn diagram analysis revealed 24 genes common for both disorders, including asthma-specific key nodes Timp1, Cyp2e1, and Muc5ac." (PMID 35625754, 2022). "It is known that TIMP-1 binds and inactivates matrix metalloproteinases (MMP), specifically MMP-2 and MMP-9, with imbalances of the MMP-9/TIMP-1 interactions posited in the development of asthma." (PMID 34221020, 2021). "The inhaled corticosteroid (ICS), beclomethasone dipropionate (BDP), attenuated the expression of submucosal MMP-9 and increased that of submucosal TIMP-1, suggesting corticosteroid treatment of asthma to ameliorate angiogenesis." (PMID 33628848, 2021). "Low sputum MMP-9/TIMP2 ratios are associated with airway narrowing in smokers with asthma and MMP-9/TIMP-1 ratios correlate inversely with airway wall thickness assessed by CT scanning in asthmatics." (PMID 33718297, 2021). "In unison with former studies, MMP-2/-9 and TIMP-1/-2 levels increased with severity of equine asthma and all MMPs/TIMP concentrations decreased with clinical score parameters within 2-6 weeks after CPG-ODN inhalation." (PMID 31316303, 2019). "Some previous studies have demonstrated an association between TIMP-1 or PDGF-BB and asthma in children." (PMID 31123265, 2019). "The same authors have stressed the potential importance of MMP-9 and TIMP-1 imbalance in asthma by showing that the basal airway caliber was related to the ratio of MMP-9 to TIMP-1." (PMID 31547356, 2019).